BPIFB1 (BPI fold containing family B member 1)
Description:
May play a role in innate immunity in mouth, nose and lungs. Binds bacterial lipopolysaccharide (LPS) and modulates the cellular responses to LPS.
Synonyms: VEMSGP; C20orf114; LPLUNC1; dJ1187J4.1; MGC14597; bA49G10.6
Tractability: Antibody: its Gene Ontology location is reachable by antibodies, with high confidence; UniProt places it where antibodies can reach, with medium confidence; UniProt predicts a signal peptide or a membrane-spanning region. PROTAC: ubiquitination databases record sites on it.
Gene: Protein-coding gene on chromosome 20 (33,273,480 to 33,310,380, forward strand). Ensembl gene ENSG00000125999.
Subcellular location: Secreted
Pathways (Reactome):
Immune System: Antimicrobial peptides
Gene Ontology:
Molecular function: lipid binding
Biological process: innate immune response in mucosa; negative regulation of toll-like receptor 4 signaling pathway
Cellular component: extracellular exosome; extracellular region
Genetic constraint (gnomAD): Loss-of-function variants: 32 observed, 54.09 expected, observed/expected ratio (o/e) 0.59, 90% interval 0.45 to 0.8. The upper end of that interval is the gene's LOEUF score, 0.8, which puts it in group 3 of 6, group 1 being the genes least tolerant of losing a copy. Missense variants: 522 observed, 604.18 expected, observed/expected ratio (o/e) 0.86, 90% interval 0.8 to 0.93. Synonymous variants: 230 observed, 251.09 expected, observed/expected ratio (o/e) 0.92, 90% interval 0.82 to 1.02.
Homologues: Orthologues: chimpanzee BPIFB1 (98% identical), macaque BPIFB1 (91% identical), dog BPIFB1 (70% identical), pig BPIFB1 (65% identical), mouse Bpifb1 (58% identical), rat Bpifb1 (56% identical), guinea pig BPIFB1 (54% identical), Caenorhabditis elegans C06E8.5 (16% identical). Paralogues in human: BPIFB4 (19% identical), BPIFB6 (18% identical), BPIFB3 (17% identical), BPIFB2 (15% identical), PLTP (15% identical), BPIFC (14% identical), BPIFA1 (14% identical), LBP (14% identical), BPI (13% identical), CETP (13% identical), BPIFA2 (12% identical), BPIFA3 (8% identical).